MCL1 (MCL1 apoptosis regulator, BCL2 family member)
Diseases named in the same sentence as MCL1 in open-access papers (continued):
Sharing a sentence is not in itself a finding about the gene and the disease.
hepatocellular carcinoma (continued). "Mcl-1 is an antiapoptotic molecule of the Bcl2 family that is extensively overexpressed in tumor tissues of patients with hepatocellular carcinoma (HCC)." (PMID 21507240, 2011). "Our study supports the concept that Mcl-1 is an important survival factor for hepatocellular carcinoma." (PMID 17014711, 2006). "The Bcl-2 family member Mcl-1 has been described to contribute to the resistant phenotype in hepatocellular carcinoma." (PMID 17014711, 2006). "Similarly, curcumin promotes both apoptosis and autophagy in hepatocellular carcinoma cells by downregulating MCL-1 expression." (PMID 41049425, 2025). "MCL-1 is a survival factor for hepatocellular carcinoma (HCC)." (PMID 33883020, 2021). "Interestingly, we also observed a regulation in the anti-apoptotic mitochondrial marker MCL-1, reinforcing the regulation of apoptosis mediated by miR-518d/c-Jun in hepatoma cells under sorafenib treatment." (PMID 34050139, 2021). "Mcl-1 plays a critical role in chemoresistance and tumorigenesis, particularly in solid cancers, such as non-small-cell lung cancer, oral squamous cell carcinomas, Non-Hodgkin's B-cell lymphomas, and hepatocellular carcinoma." (PMID 30678274, 2019). "Recently it was reported that ABT-263 treatment alone can enhance the MCL-1 mRNA and protein levels in hepatocellular carcinoma, and these cells could be sensitized to ABT-263 by inhibition of the AKT pathway." (PMID 31150457, 2019). "Moreover, regorafenib administration also modified the BCL-2/MCL-1 ratio and navitoclax sensitized hepatoma cells to regorafenib by a mitochondrial caspase-dependent mechanism." (PMID 29682179, 2018). "Moreover, the downregulation of Mcl-1 and Sox2 by ψ-Bufarenogin was markedly attenuated in hepatoma cells that were transfected with a dominant negative mutant of Akt, suggesting that Akt was involved in a ψ-Bufarenogin-mediated reduction of Mcl-1 and Sox2." (PMID 25890498, 2015). "Reconstitution of Mcl-1 expression attenuated ψ-Bufarenogin-elicited apoptosis, indicating that ψ-Bufarenogin may facilitate hepatoma cell apoptosis via Mcl-1 reduction." (PMID 25890498, 2015). "Upregulated MCL-1 in human hepatocellular carcinoma (HCC) has been demonstrated in numerous studies, and therapeutic agents targeting this protein have been assessed." (PMID 40380182, 2025). "Western blot results showed that the inhibitory effect of KPL combined with ABT-199 on the proliferation of hepatoma HepG2 cells may be related to KPL downregulating Mcl-1, thereby regulating the Bcl-2 protein family in the endogenous mitochondrial pathway of ABT-199 regulating apoptosis." (PMID 36386146, 2022). "Besides transcriptional modulation, MCL-1 expression is also tightly controlled by post-transcriptional modification, suggesting that proteasomal degradation of MCL-1 could be taking place in regorafenib-treated hepatoma cells." (PMID 32024199, 2020). "The previous research pointed out that dovitinib downregulates the p-STAT3 and subsequently reduced the levels of expression of STAT3-related proteins Mcl-1, survivin, and cyclin D1 in a time-dependent manner in human hepatocellular carcinoma (HCC)." (PMID 31485222, 2019). "For example, the spontaneous apoptosis induced by targeted deletion of mcl1 in hepatocytes results in severe liver damage and increased proliferation that actually results in hepatocellular carcinoma (HCC)." (PMID 29769323, 2018). "In addition, a good correlation was found between BCL-2/MCL-1 expression and sorafenib-induced cytotoxicity (0.938, Pearson coefficient) in the hepatoma cell lines examined, maybe supporting this ratio also as indicative of sorafenib efficacy." (PMID 29682179, 2018). "During obesity-associated hepatocellular carcinoma (HCC) development, expression of interleukin-6 (IL-6), which results from a chronic low-grade proinflammatory state in white adipose tissue and liver, helps to stabilize Mcl-1 via promotion of GSK3β inactivation and suppression of HUWE1." (PMID 30176860, 2018).
hepatocellular carcinoma (continued). "Therefore, the well-known decrease of MCL-1 induced by sorafenib, combined to BCL-xL/BCL-2 reduction by RNA silencing or ABT-263 treatment, could be enough to cause hepatoma cell death as previously reported." (PMID 29682179, 2018). "To gain further insight into the regulation of apoptosis in hepatocellular carcinoma (HCC), we investigated the TRAIL pathway and the regulators of apoptosis caspase-8, Bcl-xL and Mcl-1 in patients with HCC regarding patient survival." (PMID 24209510, 2013). "In another example, the forced expression of miR-29 sensitized hepatocellular carcinoma (HCC) cells to apoptosis under serum starvation and hypoxia conditions through a mitochondrial pathway involving Mcl-1 and Bcl-2." (PMID 23509776, 2013). "Therefore, manipulation of the antiapoptotic function of Mcl-1 by disrupting T163 site phosphorylation may represent a new strategy for treatment of hepatocellular carcinoma and/or other malignancies overexpressing Mcl-1." (PMID 21507240, 2011). "As a result, STAT3-regulated genes Bcl-2, cyclin D1, Bcl-xL, survivin, Mcl-1, and VEGF were downregulated, inhibiting proliferation and prompting substantial death in hepatocellular carcinoma cells." (PMID 38310190, 2024). "Furthermore, ablation of the anti-apoptotic protein MCL-1 in hepatocytes induces widespread induction of apoptosis in the liver and results in the spontaneous development of hepatocellular carcinoma (HCC)." (PMID 36369364, 2023). "BCL-2 and BCL-XL were inhibited by the use of navitoclax (ABT-263) in hepatocellular carcinoma (HCC) cells, however, MCL-1 mRNA and protein were stabilized, resulting in a limited effect." (PMID 36609747, 2023). "In terms of targeting FBXW7 itself, the downregulation of prolyl isomerase Pin1 contributes to upregulation of FBXW7 and ensuing destruction of MCL-1, which potentiates the toxicity of sorafenib to prevent cell proliferation and induce apoptosis in hepatocellular carcinoma (HCC)." (PMID 35515121, 2022). "A combination of inhibitory CDK can overcome the resistance of hepatocellular carcinoma cells to sorafenib, and CDK-mediated inhibition of MCL-1 plays a key role in mediating this process." (PMID 33883020, 2021). "Imperatorin potentiates the cytotoxicity of cisplatin in hepatocellular carcinoma (HCC) cells (HepG2, HepG3B, PLC, Huh7) by downregulating Mcl-1 expression." (PMID 32781533, 2020). "Our in vitro data indicates that regorafenib also increases the BCL-2/MCL-1 ratio and ABT-263 administration is able to sensitize hepatoma cells against regorafenib." (PMID 29682179, 2018). "Sorafenib-resistant hepatoma cells (HepG2R and Hep3BR) exhibited altered mRNA expression of BCL-2 and other anti-apoptotic family members, such as MCL-1, priming drug-resistant cancer cells to death by BH3-mimetics." (PMID 29682179, 2018). "For the regulation of apoptosis, miR-101 is downregulated in human hepatocellular carcinoma and can markedly inhibit the expression of the antiapoptotic factor Mcl-1 (BCL2 family apoptosis regulator), leading to apoptosis of hepatocellular carcinoma cells." (PMID 28824612, 2017). "Studies have demonstrated that depletion of MCL-1 triggers apoptosis in some cancer cells, such as non-small cell lung cancer (NSCLC) cells and hepatocellular carcinoma cells." (PMID 28659182, 2017). "Down-regulation of MCL-1 reportedly sensitizes NSCLC cells and hepatocellular carcinoma cells to apoptosis induced by chemotherapeutic agents." (PMID 28659182, 2017).
hepatocellular carcinoma (continued). "In this study, we, for the first time, found that NS4B and HCV induced the expression of four cancer-related NF-κB target genes, C-myc, Mcl-1, Cyclin D1 and MMP-9 by the EOR-Ca2+-ROS-NF-κB pathway in both human hepatoma cells and primary human hepatocytes." (PMID 25875501, 2015). "In addition, IFN α with sorafenib together downregulates the expression of Mcl-1, Bcl-2 and Bcl-xL, resulting in hepatocellular carcinoma (HCC) cell apoptosis." (PMID 26452032, 2015). "In hepatocellular carcinoma cells, niclosamide inhibits cell viability, clone formation, and induces apoptosis by deactivating STAT3 phosphorylation and downregulating antiapoptotic proteins, Mcl-1, and survivin." (PMID 37627178, 2023). "In hepatoma HepG2 cells, TSAIII treatment is reported to activate cleaved-caspase-3, caspase-8, and caspase-9, increase the expression of Mcl-1 and Bcl-2, and induce the release of cytochrome C, suggesting that TSAIII induces caspase-dependent and mitochondrial-mediated apoptosis." (PMID 36611961, 2022). "Targeting MCL-1 directly promoted apoptosis of hepatoma cells without affecting the growth of normal hepatocytes." (PMID 33883020, 2021). "Likewise, Mcl-1 depletion was shown to involve the induction of ACD by SC-59, a novel sorafenib derivative, in hepatocellular carcinoma cells." (PMID 33805467, 2021). "Genetic silencing of Mcl-1 sensitizes a spectrum of cancers, such as melanoma, non-small cell lung and hepatocellular cancers to chemotherapy." (PMID 28659182, 2017). "Hepatoma cells (SK-Hep1 and Huh 7) transfected with ISX shRNAi showed significant downregulation of E2F1 and DP1 protein expression as well as of proliferation markers (cyclin D1, c-Myc, Cdc25A, and PCNA) and anti-apoptotic genes (p65 and Mcl-1)." (PMID 27175585, 2016). "Moreover, we confirmed that high DHHC7 could be induced in c-Myc/MCL1-treated mice liver compared to health control, suggesting that DHHC7 is involved in the malignancy of hepatic carcinoma cells and MY-D-4 is a promising inhibitor for HCC treatment." (PMID 38051779, 2023). "Although Mcl-1 inhibitors represent promising hepatocellular carcinoma treatment, the still poorly understood non-apoptotic roles of Mcl-1 might compromise their successful clinical application." (PMID 37663116, 2023). "Hepatocellular carcinoma (HCC) cells were sensitized to regorafenib through the inhibition of the expression of both vascular endothelial growth factor A (VEGF-A) and myeloid cell leukemia 1 (MCL-1) by siRNA." (PMID 33922992, 2021). "In this study, we found that SAF, which was isolated from a fungal strain in our lab identified as Aspergillus aculeatus, could inhibit the progression of hepatocellular carcinoma by targeting MARCH1, which regulates the PI3K/AKT/β-catenin and antiapoptotic Mcl-1/Bcl-2 signaling cascades." (PMID 30678274, 2019). "Interestingly, ψ-Bufarenogin elicited a dose-dependent Mcl-1 reduction in hepatoma cells, but the levels of Bax and Bcl-2 were not remarkably altered." (PMID 25890498, 2015). "We analyzed 157 hepatocellular carcinoma patients who underwent partial liver resection or orthotopic liver transplantation and healthy control liver tissue using immunohistochemistry on tissue microarrays for the expression of TRAIL-R1 to TRAIL-R4, caspase-8, Bcl-xL and Mcl-1." (PMID 24209510, 2013). "Bcl-xL and Mcl-1 have been identified as major anti-apoptotic Bcl-2 proteins in the liver for previous studies revealed that Bcl-2 is not generally expressed in human hepatocytes and hepatoma cell lines." (PMID 21504623, 2011).
hepatocellular carcinoma (continued). "In hepatocellular carcinoma (HCC) cells, ketoconazole downregulates the expression of COX2, thereby triggering PINK1-Parkin-mediated mitophagy to enhance apoptosis, downregulate BCL2, BCL-XL and MCL1 and upregulate BAX and BAK." (PMID 39013891, 2024). "In hepatoma cells, HIF-1α induced MCL-1 upregulation is anti-apoptotic while in small cell lung cancer cell lines, hypoxia induced MCL-1 downregulation is independent of HIF-1α." (PMID 28404924, 2017).
glioma (79 papers, 2011 to 2025). A benign or malignant brain and spinal cord tumor that arises from glial cells (astrocytes, oligodendrocytes, ependymal cells). "Unlike aspirin and indomethacin, which have an effect on Bcl-2, Mcl-1, and Noxa, Noxa appeared to be a susceptible Bcl-2 family protein upregulated by dipyridamole which contributed to glioma apoptosis." (PMID 35054765, 2022). "Glioma patients with a high expression of Mcl-1 are associated with tumor recurrence and a shorter survival period." (PMID 35054765, 2022). "In indomethacin-treated glioma cells, activated ER stress/Ask1/p38 axis causes Akt inactivation and Mcl-1/FLIP downregulation, resulting in cell apoptosis." (PMID 33920356, 2021). "Genetic silencing of Mcl-1 augmented aspirin-induced glioma cell viability loss, while Bax or Noxa silence ameliorated it." (PMID 32545774, 2020). "Notch1, through regulation of PI3K/Akt activity and Mcl-1, has been implicated in the radioresistance of glioma initiating cells." (PMID 26716508, 2016). "It is reported that Mcl-1 is highly expressed antiapoptotic protein in malignant tumors and cause glioma cell resistance toward apoptosis induced by chemotherapy or radiation therapy." (PMID 25022352, 2014). "Altogether, we have identified in this work a Mcl-1/Bak axis implicated in TMZ induced apoptosis in two different glioma cell lines." (PMID 24811082, 2014). "Therefore, in glioma stem cells, the efficacy of Bcl-xL inhibition is closely associated with Mcl-1 activity and Noxa expression." (PMID 36273072, 2022). "We identify BCL2L1 DNA methylation as a key biomarker predicting MCL1 dependency, offering targeted MCL1 inhibitor therapy for pediatric high-grade gliomas and other cancers." (PMID 39846250, 2025). "Together, this suggests that cg00300298 methylation is a predictor of MCL1 dependency specifically in childhood glioma and emphasizes the importance of biomarker discovery in age-relevant tumor cohorts." (PMID 39846250, 2025). "Consistent with prior evidence, KO of BCL2L1 led to a concentration-dependent sensitization of both adult and pediatric gliomas toward MCL1 inhibitors." (PMID 39846250, 2025). "Collectively, these expression data show that MCL1 is a pediatric glioma–enriched genetic dependency and underscore the need for further investigation into its role in pHGGs." (PMID 39846250, 2025). "We next interrogated the methylation of cluster 1 CpG sites as a predictive biomarker for MCL1 inhibition in other CNS and non-CNS cancers." (PMID 39846250, 2025). "Taken together, these data indicate BCL-XL and MCL-1 comprise a dual apoptotic barrier to block intrinsic apoptosis across molecularly heterogeneous patient glioma tumours." (PMID 39572533, 2024). "The natural compound curcumin combined with thioridazine mediates caspase-dependent apoptotic cell death by producing NOX4-induced ROS and by downregulating c-FLIP and MCL-1 in various cancers, including breast, head and neck, and glioma." (PMID 39765861, 2024). "Consistent with our in vitro results, we found that ABBV-155 caused a single dependency on MCL-1 in both xenograft models, supporting the conclusion that ABBV-155 can ablate the BCL-XL block in orthotopic glioma xenografts." (PMID 39572533, 2024). "miR-193a-3p induced the accumulation of intracellular reactive oxygen species (ROS) and DNA damage as determined by the level of γH2AX in the glioma cell line by targeting myeloid cell leukaemia 1 (Mcl-1)." (PMID 39451223, 2024). "MCL1 silencing has been shown to lead to the senescence and apoptosis of glioma cells through the inhibition of the PI3K/Akt signaling pathway." (PMID 36231068, 2022). "With regard to the role of Notch pathway in resistance of glioma stem cells, γ-secretase inhibitors cause glioma stem cells to be more vulnerable to therapy because of PI3K/Akt activation and overexpression of truncated apoptotic isoform of Mcl-1." (PMID 35505363, 2022).